MTOR (mechanistic target of rapamycin kinase)
Diseases named in the same sentence as MTOR in open-access papers (continued):
Sharing a sentence is not in itself a finding about the gene and the disease.
cancer (continued). "Several mechanisms have been proposed, including induction of AMPK and reduction of the mTOR signaling pathway to explain the anti-cancer effects of metformin." (PMID 35317106, 2021). "With this aim in mind, each final compound was evaluated on the one hand on PI3Kα and mTOR targets in vitro, and on a representative cancer cell line panel." (PMID 34500781, 2021). "Rationale: Dysregulation of the PI3K/AKT/mTOR pathway occurs frequently in cancers, providing an attractive therapeutic target for anticancer treatments." (PMID 33995662, 2021). "AMPK signaling plays a critical role in the development of almost all cancer cells, and its mechanism is to regulate tumor progression through a variety of downstream effector molecules or pathways, such as the mTOR complex." (PMID 33816275, 2021). "In cancer, MTOR is widely recognized as a key driver and drug target, whereas the importance of SG proteins for tumorigenesis and treatment response is only beginning to emerge." (PMID 35822040, 2021). "Phosphorylation reactions, which are taking place due to the PI3K/Akt/mTOR pathway, lead to cancer cell growth, cell proliferation and angiogenesis via the depletion of inositol polyphosphate 5-phosphatase PIPP and activation of serine/threonine kinase AKT." (PMID 34357119, 2021). "PI3K/Akt not only leads to the activation of both GSK3β and mTOR but also has been found upstream of NF-κB activation in different cancers, and the NF-κB pathway is believed to be a target of Akt." (PMID 34380537, 2021). "Diseases, particularly cancers, which result from dysfunction in both mTOR and Wnt pathways, await breakthroughs in new compounds, antibodies, nucleic acid drugs, and bioengineering advances for the clinical development of the next generation of therapeutics." (PMID 33668092, 2021). "Some non-canonical signaling transduction motifs have been identified in the intracellular tail, being involved in cancer cell proliferation and survival, inhibition of autophagy, mTOR activation, and IFN-β toxicity." (PMID 34830209, 2021). "Inhibitors of mTOR, such as rapamycin and rapalogs, are not only tested for their therapeutic potential for cancer patients, but also used in research laboratories as activators of autophagy." (PMID 34206503, 2021). "mTOR is a signaling molecule that promotes protein synthesis, cell survival, and proliferation, which is usually found activated in cancer." (PMID 33800129, 2021). "Although mTOR inhibitors have therapeutic responses in many types of cancer, drug resistance inevitably develops due to activation of compensatory mechanisms." (PMID 34421360, 2021). "The mTOR signaling pathway is essential for many pathophysiological processes and is considered a major regulator of cancer." (PMID 34123955, 2021). "In the present study, we measured the expression of mTOR using a CRC tumor microarray that included 70 pairs of cancer tissues and adjacent normal tissues." (PMID 33946531, 2021). "An erroneous activation of the PI3K/AKT/mTOR pathway was observed in various types of cancers and induced malignant growth and therapy resistance." (PMID 34356619, 2021). "In this case, mTOR signaling plays a key role in maintaining the growth and survival of cancer cells." (PMID 34863080, 2021). "It has been reported that RPS6 phosphorylation regulates malignant phenotypes in several cancers induced by Akt-mTOR signaling." (PMID 34831193, 2021). "Here, we identified 11 upstream mTOR regulators (activators and suppressors) as important cancer drivers in TNBC." (PMID 34031411, 2021). "The detected mutations clustered in six distinct regions in the C-terminal half of mTOR, and these were accompanied by different cancer types, with one cluster particularly prominent in kidney cancer." (PMID 35250965, 2021). "CD44 regulates the phosphoinositide-3-kinase (PI3K)/AKT/mTOR signaling pathway and promotes the migration of cancer cells." (PMID 34361836, 2021).
cancer (continued). "Targeting the mTOR pathway has been extensively explored in cancer therapy and the first mTOR inhibitors approved were a class of rapamycin derivatives known as “rapalogs”." (PMID 34359627, 2021). "PI3K/AKT/mTOR signal transduction pathway can not only control cell metabolism, movement, survival and proliferation, but also can affect the growth and spread of cancer cells." (PMID 34135756, 2021). "Our results revealed that the BCAAs treatment reversed the cisplatin-induced mTOR signal inhibition and autophagy and restored the sensitivity of the cancer cells to cisplatin." (PMID 33568627, 2021). "The 2,863 predicted target genes were mainly enriched in the MAPK, PI3K-AKT, proteoglycans in cancer, and mTOR signaling pathways." (PMID 33816220, 2021). "Mechanistically, PI3K∂ activates the serine/threonine kinases AKT and mammalian target of rapamycin (mTOR), which leads to proliferation, differentiation, and enhanced survival of the cancer cells." (PMID 33790890, 2021). "The PI3K/Akt/mTOR signaling transduction pathway is important not only in the development and progression of cancers but also for its critical regulatory role in the tumor microenvironment." (PMID 35250965, 2021). "Several oncogenes, including MYC, phosphoinositide-3-kinase (PI3K), KRAS, protein kinase B (AKT), mechanistic target of rapamycin (MTOR), and HIF-1, are implicated in the regulation of cancer metabolic reprogramming." (PMID 34770949, 2021). "AKT, an oncogene, is highly expressed in human cancers and can be considered the central and convergent point of several growth signaling pathways, including mTOR." (PMID 33918290, 2021). "With respect to the role of the PI3K/AKT/mTOR pathway in cancer immune evasion, a link with the programmed death-1/programmed death-ligand 1 (PD-1/PD-L1) pathway is suggestive of an immunomodulatory role of the former." (PMID 33546207, 2021). "mTOR pathway belongs to the series of conserved pathways that impact upon longevity and aging-related diseases such as cancer." (PMID 34631854, 2021). "In this review, we summarize the information about the structure and function of the mTOR pathway and discuss the mechanisms of its deregulation in human cancers including genetic alterations of PI3K/AKT/mTOR pathway components." (PMID 33572326, 2021). "Everolimus is another mTOR inhibitor approved by the FDA to treat various cancers, including breast, renal carcinoma, and pancreatic neuroendocrine tumor." (PMID 34069269, 2021). "Recent studies have shown that PD-L1 promotes cancer cell growth and proliferation via mTOR signaling." (PMID 35027915, 2021). "Accordingly, FAK and mTOR also play an essential role in the regulation of cancer cell migration, invasion and metastasis as well as EMT process." (PMID 33920031, 2021). "Several biological processes, including the immune system, oxidative phosphorylation, PI3K/AKT/mTOR signaling, and the cell cycle, were found to be deregulated in both cancer and neurodegenerative disorders." (PMID 34203763, 2021). "Numerous reports indicate that mTOR is one of the most frequently activated pathways in human cancers 5, thus it attracts considerable interest as an essential target for cancer treatment." (PMID 34421360, 2021). "Since mTOR plays important roles in regulating cancer cell growth, metabolism, and protein synthesis, the inhibition of this complex is regarded as another interesting pharmacological approach to reduce the effects of a constitutive PI3K/Akt activation in GBM." (PMID 34063168, 2021). "Another study showed the key role of FOXO-mediated adaptive resistance in matrix-attached cancer cells in response to inhibition of PI3K/mTOR signaling." (PMID 33801659, 2021). "GLI1 expression has also been reported to be regulated by PI3K/AKT/mTOR signaling in several other cancers to promote tumorigenesis, including esophageal adenocarcinoma, melanoma, osteosarcoma, pancreatic cancer, ovarian cancer, and renal cancer." (PMID 34572373, 2021).
cancer (continued). "MTOR signaling is one of the key oncogenic pathways which is often deregulated in MYC-driven cancers, including NB." (PMID 34565342, 2021). "Evr is an inhibitor of mTOR that has exhibited anti-cancer efficacy in several cancers via the regulation of PI3K/AKT/mTOR signaling." (PMID 33849427, 2021). "PI3K/Akt/mTOR signaling is one of the most important intracellular pathways, which plays a role in cell proliferation, and it is a frequently activated pathway in cancer." (PMID 33663586, 2021). "The PI3K/AKT/mammalian target of rapamycin (mTOR) signaling pathway has been a major cancer target, with several candidate inhibitors investigated in oncology trials." (PMID 34385668, 2021). "A number of mTOR inhibitors have been introduced in cancer treatment and have demonstrated a good curative effect." (PMID 34812264, 2021). "Elevated PLD activity induces mitogen-activated protein kinase (MAPK) and mammalian target of rapamycin (mTOR), which act as oncogenic signals in cancer." (PMID 35127525, 2021). "Rapamycin, a specific inhibitor of mTOR, reduces phosphorylation of the mTOR targets, which potentially restrain the growth and proliferation of malignant tumors in dogs." (PMID 34124226, 2021). "It has been reported that cancer cells depend on PI3K-Akt-mTOR signaling for survival in response to DNA damage, indicating that regulating autophagy is a good tool to inhibit tumors." (PMID 34875997, 2021). "The overexpressed mTOR gene in malignant liver tumors upregulates CD133 and promotes the cytochemical resistance, which means that clinical trials show a poor prognosis." (PMID 33494431, 2021). "Both the Wnt/β-catenin pathway and the phosphatidylinositol-3-kinase/Akt/mechanistic target of rapamycin complex 1 (PI3K/Akt/mTOR) pathway are upregulated in many cancers." (PMID 33987182, 2021). "Aberrant CCR is also induced by malfunction of PI3K/AKT/mTOR, a cell survival pathway disrupted in both AD and cancer, though in opposite directions." (PMID 34243793, 2021). "Although these results were obtained from cancer research, HTS development is closely highly associated with PI3K/Akt/mTOR signaling pathway and can also be influenced through manipulating and stem cells." (PMID 34715879, 2021). "Evidence indicates that the PI3K/AKT/mTOR pathway contributes to cancer cell growth and progression." (PMID 35010954, 2021). "The mammalian or mechanistic target of rapamycin (mTOR) pathway plays a vital role in cancer and regulates cell survival, metabolism, growth, and protein synthesis." (PMID 34194607, 2021). "Once activated by decreased cellular ATP/AMP ratio, AMPK stimulates catabolic pathways to maintain a sufficient energy supply and negatively regulates its downstream effector mTOR, thus modulating cancer cell proliferation, invasion and metastasis." (PMID 34772914, 2021). "Although many small molecule inhibitors targeting the PI3K/AKT/mTOR signaling pathway were pre-clinically studied, only some of the PI3K and mTOR inhibitors are currently approved for the treatment of human cancers in the clinic." (PMID 34298731, 2021). "Studies have indicated that the mTOR pathway is a key regulator of glycolysis and plays an important role in the growth, survival, and migration of cancer cells." (PMID 33771982, 2021). "Given that the PI3K/AKT/mTOR axis is frequently activated in cancer cells to sustain proliferation and survival, we examined the status of AKT in response to miR1908 targeting." (PMID 34887471, 2021). "In TNBC cells, PGRMC1 plays a prominent role in regulating the growth of cancer cells by altering the PI3K/AKT/mTOR and EGFR signaling mechanisms." (PMID 34746100, 2021). "Following on from the early success of rapamycin in certain clinical settings an enormous effort was made to effectively target mTOR in cancer." (PMID 33810522, 2021). "Inhibitors targeting PI3K-Akt-mTOR pathway had shown promising efficacy in improving immunotherapy response in selected cancer type." (PMID 33874915, 2021).
cancer (continued). "The activation of the mTOR signaling pathway can promote the immune escape of cancer by promoting the expression of PD-L1." (PMID 34394184, 2021). "Considering that the PI3K/Akt/mTOR axis is a therapeutic target for many diseases, especially cancers, we believe it is meaningful to delve into research in TanIIa and other active substances of Radix Salviae Miltiorrhizae." (PMID 34691211, 2021). "MUC1 promotes proliferation and invasion of cancer cells through the activation of the PI3K/Akt/mTOR and ERK1/ERK2 pathways." (PMID 34770912, 2021). "Melatonin has been shown to function at multiple levels to halt cancer cell proliferation via the mTOR, MAPK, EGF (and other) pathways responding to several growth factors." (PMID 33920158, 2021). "The results indicate that ovalitenone suppressed EMT and AKT/mTOR signals, which are important controllers of cancer cell migration, invasion, and metastasis." (PMID 33530617, 2021). "Our recent work has demonstrated that one of the mTOR complexes, mTORC2, is a strong acetylation driver in cancer cells, especially in the context of EGFR-mutant genotypes." (PMID 33916219, 2021). "The anabolic resistance in cancer-induced muscle wasting seems to be attenuated by resistance exercise training through improvement in mammalian target of rapamycin (mTOR) signaling." (PMID 34436458, 2021). "Top classes of mechanism of action amongst targeted cancer compounds included PI3K/AKT/MTOR, EGFR, and HDAC inhibitors." (PMID 34907286, 2021). "In particular, the cancer-inhibitory effects of naringin have been linked to the regulation of various signaling pathways, such as Nrf2, NF-κB, PI3K/Akt/mTOR, JNK, ERK, and p38 MAPK." (PMID 33854437, 2021). "Inhibition of PI3K/AKT/mTOR signaling in cancer represents a promising therapeutic strategy, with isoform-selective PI3Kα inhibitors showing greater efficiency and less toxicity than pan-PI3K inhibitors." (PMID 34395258, 2021). "Abnormal activation of PI3K/AKT/mTOR signaling is an important mechanism for promoting cancer biology." (PMID 34306145, 2021). "In this regard, cancer cells often overactivate mTOR, which upregulates the translocation of the glucose transporter GLUT1 to the plasma membrane." (PMID 34572839, 2021). "Dysregulation of the mTOR pathway is frequently reported in many types of human tumors, and targeting the PI3K/Akt/mTOR signaling pathway has been considered an attractive potential therapeutic target in cancer." (PMID 35250965, 2021). "For instance, miR-7, miR-99a, miR-338, miR-375 and miR-382 directly target mTOR to regulate autophagy, thereby disturbing the tumorigenic potential of cancer cells 46-50." (PMID 33390839, 2021). "The PI3K/Akt and mTOR signaling pathways are essential for maintaining the proliferation and survival of cancer cells." (PMID 34335799, 2021). "The PI3K/Akt/mTOR signaling pathway has been reported to participates in cancer cells proliferation and metastasis." (PMID 34580235, 2021). "The activated Akt pathway then stimulates mTOR and p70S6 kinase to participate in protein synthesis and cell growth, inducing the promotion of cancer cell survival." (PMID 34503536, 2021). "The PI3K/AKT/mTOR signaling pathway is overactivated in many tumors and participates in cancer invasion." (PMID 33763366, 2021). "The importance of mTOR in cell-cycle regulation reinforces the interest in using mTOR inhibitors in clinics as powerful anti-proliferative compounds, and for many cancer clinical trials as front-line therapy or alternative treatment to overcome resistance." (PMID 35008317, 2021). "Recently, small molecule inhibitors have been designed to interrupt the DEPTOR PDZ/mTOR interaction and have shown selective cytotoxicity against this type of cancer." (PMID 34519269, 2021). "Aberrant mTOR signaling is involved in various pathological conditions such as cancer and inflammation as well as cardiovascular and metabolic disorders." (PMID 33768214, 2021).
cancer (continued). "Considering that mTOR inhibition is currently being explored in numerous clinical trials for cancer therapy, we decided to verify this finding by a second approach." (PMID 34066490, 2021). "There are also polyprenylated xanthone/benzophenone derivatives, such as gambogic acid and isogambogenic acid, known to trigger autophagy and/or apoptosis in cancer cells via the mTOR pathway." (PMID 34586597, 2021). "α7-nAChR and EGFR are both enhance the cancer cell proliferation via activation of the PI3K/AKT/mTOR signaling pathway, and PTEN is a major negative regulator of this pathway." (PMID 34595181, 2021). "Due to mutation, amplification, deletion, methylation and post-translational modifications, mTOR overactivation in NSCLC is essential for tumorigenesis, cancer progression and therapy resistance, and is often associated with poor prognosis." (PMID 33824293, 2021). "Activation of MTOR promotes tumor growth and metastasis, and many MTOR inhibitors have been developed to treat cancer." (PMID 33632303, 2021). "PI3K/Akt/mTOR pathway activity is frequently upregulated in cancer as it is involved in the regulation of cell proliferation, growth, cell size, metabolism, and motility." (PMID 34572839, 2021). "In NB and other cancers, MYCN and mTOR signaling have been shown to play key roles in cancer stem cells and contribute to relapse and drug-resistance." (PMID 34565342, 2021). "The PIK3/AKT/mTOR (PAM) pathway is considered a master regulator of cancer and plays a vital role in tumor growth, proliferation, angiogenesis, and cell survival." (PMID 33619913, 2021). "NB cells, like many cancer cells, possess an aberrant activation mammalian target of rapamycin (mTOR) signaling pathway which has been evidenced in our previous studies." (PMID 33456359, 2021). "Reflecting its physiological importance, the PI3K/mTOR pathway represents one of the most frequently deregulated pathways in cancer." (PMID 34203293, 2021). "Niclosamide, a dual inhibitor of STAT3 and mTOR, was selected not only because of its efficacy against cancer and its synergistic effects with many other drugs; but because the mTOR pathway is parallel to STAT3–NF-κB axis." (PMID 34223559, 2021). "This is consistent with previous studies where PI3K/mTOR dual inhibitors showed antineoplastic properties in various cancer cell lines." (PMID 34065268, 2021). "LAT1 transports large neutral amino acids, including leucine, which activates mTOR, and is highly expressed in human cancers." (PMID 34194623, 2021). "In the past three decades, studies have been exponentially expanded to map the landscape of the mTOR pathway, providing insightful knowledge for targeting this fundamental pathway to treat human diseases, particularly cancers." (PMID 33670113, 2021). "Aberrant activation of the PI3K/AKT/mTOR signaling pathway is demonstrated in many human cancers and promotes tumor progression." (PMID 34770912, 2021). "Studies on PI3K/AKT/mTOR signaling pathway showed that cancer cells were strongly addicted to glucose and other nutrients such as amino acids." (PMID 33849550, 2021). "The mTOR and Wnt cancer cell signaling pathways, and indeed all major mammalian cell growth pathways, have diverse extracellular activating and inhibiting ligands and multiple points of intersection." (PMID 33668092, 2021). "There have been many advances in understanding the PI3K/AKT/mTOR signaling pathway, as this pathway is frequently altered in human cancer." (PMID 34831441, 2021). "In this regard, a large number of miRNAs were found to be involved in the regulation of PI3K/Akt/mTOR activity, a pathway promoting cell growth, and protein and lipid biosynthesis in cancer cells." (PMID 34681797, 2021). "Meanwhile, as a critical pathway and potential drug target in cancer development, Akt/mTOR signaling stimulates cell proliferation at various stages of the cell cycle." (PMID 33777755, 2021).